C3orf85 (chromosome 3 open reading frame 85)
Synonyms: FLJ22763
Gene: Protein-coding gene on chromosome 3 (109,118,252 to 109,152,132, forward strand). Ensembl gene ENSG00000241224.
Homologues: Orthologues: chimpanzee C3orf85 (98% identical), macaque C2H3orf85 (93% identical), dog C3orf85 (78% identical), guinea pig C3orf85 (77% identical), pig C3orf85 (77% identical), mouse Gm5485 (61% identical), rat Gm5485 (61% identical).
Diseases named in the same sentence as C3orf85 in open-access papers:
C3orf85 is named in the same sentence as 1 disease in open-access papers, as found by Europe PMC text mining. Sharing a sentence is not in itself a finding about the gene and the disease. The quoted sentences say what the papers report.
Crohn disease (1 paper, 2026). A gastrointestinal disorder characterized by chronic inflammation involving all layers of the intestinal wall, noncaseating granulomas affecting the intestinal wall and regional lymph nodes, and transmural fibrosis. "C3orf85 is involved in protein-coding processes; its mRNA expression level is higher in the colonocytes of patients with noninflammatory bowel disease than in those of patients with Crohn’s disease." (PMID 40808558, 2026).